CD63 (CD63 molecule)
Description:
Functions as a cell surface receptor for TIMP1 and plays a role in the activation of cellular signaling cascades. Plays a role in the activation of ITGB1 and integrin signaling, leading to the activation of AKT, FAK/PTK2 and MAP kinases. Promotes cell survival, reorganization of the actin cytoskeleton, cell adhesion, spreading and migration, via its role in the activation of AKT and FAK/PTK2. Plays a role in VEGFA signaling via its role in regulating the internalization of KDR/VEGFR2. Plays a role in intracellular vesicular transport processes, and is required for normal trafficking of the PMEL luminal domain that is essential for the development and maturation of melanocytes. Plays a role in the adhesion of leukocytes onto endothelial cells via its role in the regulation of SELP trafficking. May play a role in mast cell degranulation in response to Ms4a2/FceRI stimulation, but not in mast cell degranulation in response to other stimuli.
Synonyms: MLA1; TSPAN30; ME491; HOP-26; Pltgp40; AD1; OMA81H
Tractability: Antibody: UniProt places it where antibodies can reach, with high confidence; its Gene Ontology location is reachable by antibodies, with high confidence; UniProt predicts a signal peptide or a membrane-spanning region. PROTAC: ubiquitination databases record sites on it; its protein half-life has been measured; a small molecule that binds it is known.
Target class: Surface antigen
Gene: Protein-coding gene on chromosome 12 (55,723,511 to 55,730,023, reverse strand). Ensembl gene ENSG00000135404.
Subcellular location: Cell membrane; Lysosome membrane; Late endosome membrane; Endosome, multivesicular body; Melanosome; Secreted, extracellular exosome; Cell surface
Subcellular location (Human Protein Atlas): Vesicles
Pathways (Reactome):
Hemostasis: Platelet degranulation
Immune System: Neutrophil degranulation
Gene Ontology:
Molecular function: protein binding; protein-containing complex binding
Biological process: cell migration; cell-matrix adhesion; endosome to melanosome transport; pigment granule maturation; positive regulation of integrin-mediated signaling pathway; positive regulation of receptor internalization; regulation of potassium ion transmembrane transport; regulation of vascular endothelial growth factor signaling pathway; cell differentiation; epithelial cell differentiation; negative regulation of epithelial cell migration; pigment cell differentiation; pigmentation; positive regulation of cell adhesion; positive regulation of endocytosis
Cellular component: cell surface; endosome lumen; endosome membrane; extracellular exosome; extracellular region; late endosome membrane; lysosomal membrane; melanosome; multivesicular body membrane; multivesicular body, internal vesicle; plasma membrane; azurophil granule membrane; platelet dense granule membrane; late endosome; lysosome; membrane; multivesicular body; protein-containing complex; vesicle
Genetic constraint (gnomAD): Loss-of-function variants: 16 observed, 30.36 expected, observed/expected ratio (o/e) 0.53, 90% interval 0.36 to 0.8. The upper end of that interval is the gene's LOEUF score, 0.8, which puts it in group 3 of 6, group 1 being the genes least tolerant of losing a copy. Missense variants: 251 observed, 313.67 expected, observed/expected ratio (o/e) 0.8, 90% interval 0.72 to 0.89. Synonymous variants: 118 observed, 117.93 expected, observed/expected ratio (o/e) 1, 90% interval 0.86 to 1.17.
Homologues: Orthologues: macaque CD63 (100% identical), chimpanzee CD63 (99% identical), dog CD63 (89% identical), rabbit CD63 (88% identical), pig CD63 (86% identical), guinea pig CD63 (79% identical), mouse Cd63 (79% identical), rat Cd63 (78% identical), tropical clawed frog cd63 (48% identical), zebrafish cd63 (42% identical), Caenorhabditis elegans tsp-7 (26% identical), Drosophila melanogaster Tsp47F (22% identical). Paralogues in human: TSPAN7 (31% identical), TSPAN4 (30% identical), TSPAN3 (29% identical), TSPAN33 (29% identical), TSPAN9 (29% identical), TSPAN6 (28% identical), TSPAN14 (28% identical), TSPAN17 (28% identical), CD151 (27% identical), TSPAN5 (26% identical), CD82 (26% identical), TSPAN8 (26% identical), and 20 more.
Diseases named in the same sentence as CD63 in open-access papers:
CD63 is named in the same sentence as 260 diseases in open-access papers, as found by Europe PMC text mining. Sharing a sentence is not in itself a finding about the gene and the disease. The quoted sentences say what the papers report.
breast carcinoma (116 papers, 2010 to 2026). "Unfortunatelly, few studies have evaluated the association between CD63 expression and clinical features or survival in breast cancer." (PMID 39430073, 2024). "Our results differ from other publications that indicate CD63 levels and other tetraspanins are associated with aggressive features and poor prognosis in various malignancies including breast cancer." (PMID 39430073, 2024). "Breast cancer-associated fibroblast-derived exosomes are enriched in tetraspanins, such as CD63, CD81, and CD82, whereas only CD81 is responsible for the transport of Wnt 11 cargo to exosomes." (PMID 36611951, 2022). "A recent study identified a central driver of EMT, integrin-linked kinase (ILK), as a cargo of CD63 positive (CD63+) EVs secreted from breast cancer cells." (PMID 34205051, 2021). "In previous studies, CD63 has been associated with tumour metastasis in other tumours including melanoma and breast cancer." (PMID 33277798, 2021). "When immunostaining assay was performed using clinical breast cancer biopsy, the CD63-1 aptamer demonstrated a comparable diagnostic efficacy for CD63 positive breast cancer with commercial antibodies." (PMID 33261145, 2020). "CD63 is generally related with less invasiveness in many cancer types, the exception of breast cancer cells in which CD63 has been linked with increased invasiveness and drug resistance, which results from CD63 glycosylation and membrane localization." (PMID 27589561, 2016). "Taken together, these results indicated that high glycosylation of CD63 by RPN2 is implicated in clinical outcomes in breast cancer patients." (PMID 24884960, 2014). "Based on the sandwich ELISA principle, isolated EVs were captured by anti-CD63 modified magnetic beads and subsequently bound by breast cancer-associated markers (EpCAM, PSMA, HER2, EGFR, CEA, CA125) serving as detection probes, with sensing completed via TMB oxidation-induced color change." (PMID 41404198, 2025). "Furthermore, single-cell profiling of myeloid cells from patients with breast cancer identified lipid-associated macrophages that co-expressed the TTR macrophage markers CD63, LIPA, GPNMB, MCR1, CD163, and MSR1." (PMID 38942020, 2024). "In addition, CD63 was identified when machine learning was applied to GWAS data with respect to radiation-associated contralateral breast cancer." (PMID 37345113, 2023). "Inhibition of RPN2 expression was found to reduce breast cancer malignancy by reducing CD63 glycosylation and modulating translocation of CD63, which is a cell surface glycoprotein with N-linked glycosylation that regulates cell motility, invasion, and cell signaling of tumors." (PMID 29069815, 2017). "Next, we performed a co-immunofluorescence analysis in breast cancers and their matched, LN metastatic carcinomas from 48 patients to clarify whether CD63 and MDR1 co-localization is associated with LN metastasis." (PMID 24884960, 2014). "In breast cancer, one study identified a subset of Cluster of Differentiation 63 (CD63+) CAFs in ER-positive breast cancer that are enriched in tumors resistant to CDK4/6 inhibitors (CDK4/6i)." (PMID 40940809, 2025). "Our InCell ELISA results reveal that both Her2-negative MCF-7 and Her2-positive SK-BR3 breast cancer cell lines exhibit comparable baseline expression of CD63, a canonical exosomal marker indicative of active exosomal biogenesis." (PMID 40806778, 2025). "Previous studies have demonstrated that RPN2-mediated glycosylation of CD63 correlates with the malignancy of breast cancer cells." (PMID 40963867, 2025). "Studies have shown that defensin disrupts breast cancer cell growth and metastasis by interfering with exosomal CD63 and CD9 recruitment." (PMID 40573239, 2025). "Another study identified a subset of CD63+ CAFs in Estrogen Receptor Alpha (Erα)-positive breast cancer that contributes to tamoxifen resistance." (PMID 40940809, 2025).
breast carcinoma (continued). "In this study, we evaluated the correlation between the expression of CD44, CD63 and clinicopathological features, including the level of TIL and PIK3CA mutations, as well as survival in a Peruvian breast cancer series." (PMID 39430073, 2024). "Specifically, the evaluation of the proportion of CD63/EpCAM/MUC1-triplepositive EVs in breast cancer can be enhanced through the analysisof these EVs at an individual level." (PMID 39175406, 2024). "Findings also indicate the significant elevation of a matrix metalloproteinase 1 (MMP1) and CD63 complex in the urine of breast cancer patients." (PMID 38250812, 2023). "For example, exosomes from prostate and breast cancer sources express more CD63 molecules, which suggests that exosomes can be used as diagnostic markers for tumors." (PMID 37848835, 2023). "The Genes‐to‐Systems Breast Cancer Database, a resource that integrates data about genes, transcripts, and proteins altered in breast cancer, shows a ratio value of CD63 expression for breast ductal carcinomas compared to normal tissue of 0.2281." (PMID 37081824, 2023). "The CD63 protein is commonly found on most cellular exosomes, while the EpCAM protein is abundantly expressed in exosomes secreted by human breast cancer cells." (PMID 37811123, 2023). "Of note, ITGAV was very low in normal adjacent breast tissues collected from four anonymized breast cancer patients although CD63 was high in all of these samples." (PMID 35923105, 2022). "They used EVs collected from the culture supernatant of MDA-MB-231 human breast cancer cells and anti-human CD63 antibody and immunoglobulin G (IgG) as EV markers." (PMID 35056304, 2022). "The only exception to this characteristic is a novel subset of CD63+ CAFs that mediated resistance to tamoxifen in breast cancers via exosomal miR-22." (PMID 35326670, 2022). "In another study, EVs derived from breast cancer cells expressing CD63-RFP fusion protein on their surface were injected intravenously in mice." (PMID 36232613, 2022). "For example, a CD-63-1 aptamer was designed for the isolation of EVs 50–150 nm in diameter from tumor samples which are positive for CD-63, considered to be a biomarker in certain types of cancers, including breast cancer." (PMID 35056304, 2022). "We quantified the expression of CD63 surface protein markers on exosomes from conditioned culture media of breast cancer cells." (PMID 36080806, 2022). "Results from ELISA showed a range of 0.5–0.8 pg/mL of CD63-positive exosomes in serum from breast cancer patients with cerebral metastases." (PMID 35409043, 2022). "Here, we present data showing that CAF-derived TIMP-1 activates STAT3 in breast cancer cells in cooperation with CD63 and integrin β1." (PMID 36291767, 2022). "Integrin αv colocalizes with the multivesicular‐body marker CD63 at a higher frequency in the tumour and is enriched in circulating EVs of breast cancer patients at late stages when compared with circulating EVs from early‐stage patients." (PMID 35923105, 2022). "Just like CD9, CD63 plays a part in the regulation of breast cancer cell malignancy and the therapy resistance to tamoxifen." (PMID 36555738, 2022). "In another study, antibodies to CD9 and CD63, glycoprotein receptors present on the surface of EVs, were used to deplete EVs in a xenograft mouse model of breast cancer." (PMID 33842540, 2021). "Changes in the expression of breast cancer marker CD63 were also observed during disease progression." (PMID 34579762, 2021). "Decreased expression of CD63 and CD9 was associated with metastatic potential in patients with breast cancer, colon cancer, pancreatic cancer and Melanoma." (PMID 34316329, 2021). "By identifying and implementing signatures of CD81+CD63+EVs within the TCGA, we were able to circumvent the differences in the immune microenvironment in mouse tumors such as 4T1 and human breast cancers." (PMID 34503207, 2021).
breast carcinoma (continued). "In the same year, single-stranded DNA was found to improve the peroxidase activity of g–C3N4 nanosheets, yielding a four-fold increase in the colorimetric analysis of exosomal CD63 in breast cancer cells." (PMID 34940275, 2021). "In other tumours including lung cancer and breast cancer, low CD63 expression is correlated with poor prognosis of patients." (PMID 33277798, 2021). "In the current study, we made an interesting observation that increased TIMP-1 expression and its activity via CD63 correlate with malignant phenotypes of breast carcinoma using the MCF10A progression model." (PMID 34685701, 2021). "Continuing with the same concepts, Qiao and his team reported a system for identifying exosomal CD63 derived from breast cancer cells from serum samples." (PMID 34940275, 2021). "Low expression of CD63 and CD9 was associated with poor prognosis in patients with breast cancer, pancreatic cancer, and lung cancer." (PMID 34316329, 2021). "Most importantly, the pharmacological blockade of CD63+ CAFs with a CD63‐neutralizing antibody or cRGD‐miR‐22‐sponge nanoparticles enhances the therapeutic effect of tamoxifen in breast cancer." (PMID 33173749, 2020). "Here, we have shown that there exists a specific CAF subset in the breast cancer microenvironment: CD63+ CAFs." (PMID 33173749, 2020). "We also evaluated the prevalence of CD63+ CAFs in human breast cancer tissues by confocal microscopy." (PMID 33173749, 2020). "To further explore the clinical significance of CD63+ CAFs in breast cancer, we generated a gene signature to evaluate the abundance of CD63+ CAFs in primary breast tumors and performed an analysis with the TCGA dataset." (PMID 33173749, 2020). "Antibodies against human CD9 and CD63, two well-established sEV surface markers, were shown to disrupt oncogenic sEVs and inhibit tumor metastasis in a breast cancer xenograft nude mouse model." (PMID 32847103, 2020). "We previously generated MCF7 (ER positive) and MDA-MB-231 (triple negative) breast cancer cell lines that stably express GFP-tagged CD63, a general surface marker of exosomes." (PMID 30782165, 2019). "They prepared GFP‐tagged CD63‐expressing breast cancer cells, co‐cultured the cells with mouse lung tissue cells, and observed green fluorescence in the lung tissue cells." (PMID 26700550, 2016). "Upon injection into immunodeficient mice, breast cancer cells expressing CD63-GFP formed tumors that metastasized to the lungs, secreting fluorescent exosomes into both the primary tumor and metastatic microenvironment." (PMID 26601108, 2015). "DHA treatment reduced tube formation by the EA.hy926 cells when co-cultured with the wildtype or CD63-GFP breast cancer cells." (PMID 26178901, 2015). "In particular, several groups have utilized breast cancer cell lines overexpressing the exosomal marker CD63 with a green fluorescent protein (GFP) fusion tag." (PMID 26601108, 2015). "The molecular weight of glycosylated CD63 decreased after treatment with N-glycanase in both breast cancer cell lines, suggesting that the smeared band represents the glycosylated form of CD63." (PMID 24884960, 2014). "Taken together, these results indicated that deregulation of CD63 attenuated drug resistance as well as invasiveness in breast cancer cells." (PMID 24884960, 2014). "In this study, we demonstrate that RPN2 promotes cancer cell malignancy in breast cancer cells through the regulation of CD63 glycosylation." (PMID 24884960, 2014). "A recent study utilized GFP-tagged CD63 expressing breast cancer cells to examine the fate of cancer-cell derived exosomes in a nude mouse model of breast cancer." (PMID 23839094, 2013). "We confirmed that breast cancer cells secreted around 100-nm size of vesicles with a consistent size and uniform expression of known exosome marker, CD63 and HP70." (PMID 23439645, 2013).
breast carcinoma (continued). "In order to define the processes of exosomal secretion and uptake, we stably transfected BT-549 breast cancer cells with green fluorescent protein (GFP)-tagged CD63 and followed the secretion and uptake of the GFP-labeled exosomes." (PMID 21915303, 2011). "Moreover, silencing CD63 led to decreased drug resistance and invasive capabilities in breast cancer cells, highlighting its contribution to tumor aggressiveness and potential therapeutic targeting." (PMID 40963867, 2025). "Moreover, since the five proteins CD9, CD24, CD63, CD81, and MMP9 are universal and present in exosomes secreted by both primary endotheliocytes and breast carcinoma cells, they cannot be part of the diagnostic panels being developed." (PMID 40310419, 2025). "For other TM4SF members, it was found that the glycosylation of CD63 was found downregulated by the knockdown of RPN2 (which is part of an N-oligosaccharyle transferase complex) in breast cancer, and silencing CD63 suppressed the chemoresistance and aggressiveness of tumor cells." (PMID 38389703, 2024). "Finally, in breast cancer cells, iNOS-associated Akt activation necessitates TIMP1 protein nitration and TIMP1 and CD63 protein-protein interactions." (PMID 39737957, 2024). "CD44 and CD63 were stained in samples from 101 breast cancer cases from Peruvian women." (PMID 39430073, 2024). "To determine whether CD74 expression correlated with that of TIMP‐1 breast cance, we examined TIMP‐1, CD74, and CD63 protein levels in tumor cells in a set of 43 breast cancer tumors." (PMID 37081824, 2023). "Furthermore, CD63 silencing reduces the chemoresistance of breast cancer cells by stabilizing MDR1 on cell surface." (PMID 36941633, 2023). "RPN2 promotes docetaxel resistance in breast cancer cells by mediating CD63 glycosylation." (PMID 36439123, 2022). "In addition, we also found that colocalization of integrin αv and CD63 was highly associated with lymph‐node and distant metastasis in breast cancer patients, consistent with ITGAV‐CD63 colocalization in xenografted CA1a tumours." (PMID 35923105, 2022). "Additionally, it has been shown that CD9 and CD63 are present in distinct structures in human platelets as well as in mouse breast cancer cells and HeLa cells." (PMID 35524458, 2022). "To confirm if ITGAV could be released in tumour‐derived EVs, we analysed the colocalization of ITGAV and CD63 in tumours using a tissue array collected from 128 breast cancer patients at the Singapore National University Hospital." (PMID 35923105, 2022). "In the future, the effect of combined treatments of anti-CD63 and chemotherapy drugs on animal breast cancer models could be investigated to reduce primary tumor growth while decreasing metastatic activity." (PMID 33842540, 2021). "Thus, in human breast cancers, tumors with signatures of high CD81+CD63+EVs are more pro-inflammatory and associated with better clinical outcomes." (PMID 34503207, 2021). "Furthermore, we confirmed that CRISPR depletion of PINK1 opposed release of CD63-postive EVs from cells derived from a mouse mammary carcinoma driven by the PyMT oncogene." (PMID 34623384, 2021). "Based on the mice data, we hypothesized that the inability to form tumors can be associated with immune response, and thus we sought to directly understand the impact of CD81+CD63+EVs and the link to the immune system within human patients with breast cancer." (PMID 34503207, 2021). "We developed and validated a platform based on nanowell arrays for directly profiling EV secretion from single cells and used these to establish cells derived from a clinically relevant mouse breast cancer model that have significant differences in the rate of secretion of CD81+CD63+EVs." (PMID 34503207, 2021). "In another case, it was found that CD63 could mediate breast cancer malignancy through glycosylation regulation." (PMID 33261145, 2020).